LINC01181 (long independently transcribed non-coding RNA 1181)
Synonyms: FLJ10489
Gene: Long non-coding RNA gene on chromosome 8 (103,121,032 to 103,132,966, forward strand). Ensembl gene ENSG00000250929.
Diseases named in the same sentence as LINC01181 in open-access papers:
LINC01181 is named in the same sentence as 1 disease in open-access papers, as found by Europe PMC text mining. Sharing a sentence is not in itself a finding about the gene and the disease.
LINC01181 shares sentences with these, for which no sentence is quoted: leprosy (1 paper).